PKIG (cAMP-dependent protein kinase inhibitor gamma)
Description:
Extremely potent competitive inhibitor of cAMP-dependent protein kinase activity, this protein interacts with the catalytic subunit of the enzyme after the cAMP-induced dissociation of its regulatory chains.
Synonyms: PKI-gamma
Tractability: Antibody: the Human Protein Atlas places it where antibodies can reach.
Gene: Protein-coding gene on chromosome 20 (44,531,762 to 44,624,247, forward strand). Ensembl gene ENSG00000168734.
Subcellular location (Human Protein Atlas): Cytosol; Nucleoplasm; Plasma membrane; Vesicles
Gene Ontology:
Molecular function: protein binding; cAMP-dependent protein kinase inhibitor activity
Cellular component: cytoplasm; nucleus
Genetic constraint (gnomAD): Loss-of-function variants: 1 observed, 4.36 expected, observed/expected ratio (o/e) 0.23, 90% interval 0.08 to 1.08. That is too few expected variants to judge how well the gene tolerates losing a copy. Missense variants: 49 observed, 73.67 expected, observed/expected ratio (o/e) 0.67, 90% interval 0.53 to 0.84. Synonymous variants: 27 observed, 30.47 expected, observed/expected ratio (o/e) 0.89, 90% interval 0.65 to 1.22.
Homologues: Orthologues: chimpanzee PKIG (100% identical), macaque PKIG (99% identical), pig PKIG (95% identical), mouse Pkig (91% identical), rat Pkig (91% identical), guinea pig PKIG (87% identical), rat LOC134479283 (61% identical), tropical clawed frog pkig (51% identical), zebrafish pkig (47% identical). Paralogues in human: PKIA (32% identical), PKIB (26% identical).
Diseases named in the same sentence as PKIG in open-access papers:
PKIG is named in the same sentence as 4 diseases in open-access papers, as found by Europe PMC text mining. Sharing a sentence is not in itself a finding about the gene and the disease. The quoted sentences say what the papers report.
cancer (2 papers, 2024 to 2025). A tumor composed of atypical neoplastic, often pleomorphic cells that invade other tissues. "Exon skipping in genes such as TUBB6, FGFR1, cAMP-dependent protein kinase inhibitor gamma (PKIG), and METTL5 was observed, which could lead to the development of cancer or affect a normal function of nervous system." (PMID 40395612, 2024).
PKIG also shares sentences with these, for which no sentence is quoted: tumor (2 papers); atherosclerosis (1); essential thrombocythemia (1).